NPIPA6 (nuclear pore complex interacting protein family, member A6)
Synonyms: NPIPA5L
Tractability: No criterion of Open Targets' tractability assessment is met for any kind of drug.
Gene: Protein-coding gene on chromosome 16 (16,317,444 to 16,350,608, forward strand). Ensembl gene ENSG00000183889.
Subcellular location (Human Protein Atlas): Nucleoplasm
Homologues: Paralogues in human: NPIPA9 (100% identical), NPIPA7 (99% identical), NPIPA8 (99% identical), NPIPA5 (94% identical), NPIPA1 (94% identical), NPIPA2 (88% identical), NPIPA3 (88% identical), NPIPB2 (73% identical), NPIPB12 (70% identical), NPIPB13 (70% identical), NPIPB4 (69% identical), NPIPB5 (69% identical), and 7 more.